MKLN1 (muskelin 1)
Description:
Component of the CTLH E3 ubiquitin-protein ligase complex that selectively accepts ubiquitin from UBE2H and mediates ubiquitination and subsequent proteasomal degradation of the transcription factor HBP1. Required for internalization of the GABA receptor GABRA1 from the cell membrane via endosomes and subsequent GABRA1 degradation (By similarity). Acts as a mediator of cell spreading and cytoskeletal responses to the extracellular matrix component THBS1.
Synonyms: TWA2
Tractability: Antibody: the Human Protein Atlas places it where antibodies can reach. PROTAC: ubiquitination databases record sites on it; its protein half-life has been measured.
Gene: Protein-coding gene on chromosome 7 (131,110,096 to 131,496,632, forward strand). Ensembl gene ENSG00000128585.
Subcellular location: Cytoplasm; Cytoplasm, cytosol; Nucleus, nucleoplasm; Cell projection, ruffle; Cytoplasm, cell cortex; Synapse; Postsynapse
Subcellular location (Human Protein Atlas): Cytosol; Plasma membrane; Vesicles
Pathways (Reactome):
Metabolism: Regulation of pyruvate metabolism
Gene Ontology:
Molecular function: identical protein binding; protein binding; protein homodimerization activity
Biological process: actin cytoskeleton organization; cell-matrix adhesion; proteasome-mediated ubiquitin-dependent protein catabolic process; regulation of cell shape; regulation of receptor internalization; signal transduction; neurotransmitter receptor transport postsynaptic membrane to endosome
Cellular component: cytoplasm; ubiquitin ligase complex; cell cortex; cytosol; GID complex; postsynapse; ruffle; synapse; GABA-ergic synapse; nucleoplasm; postsynaptic endosome membrane; postsynaptic specialization membrane of symmetric synapse
Genetic constraint (gnomAD): Loss-of-function variants: 13 observed, 46.61 expected, observed/expected ratio (o/e) 0.28, 90% interval 0.18 to 0.44. The upper end of that interval is the gene's LOEUF score, 0.44, which puts it in group 1 of 6, group 1 being the genes least tolerant of losing a copy. Missense variants: 391 observed, 544.15 expected, observed/expected ratio (o/e) 0.72, 90% interval 0.66 to 0.78. Synonymous variants: 190 observed, 193.4 expected, observed/expected ratio (o/e) 0.98, 90% interval 0.87 to 1.11.
Homologues: Orthologues: chimpanzee MKLN1 (99% identical), dog MKLN1 (99% identical), macaque MKLN1 (99% identical), mouse Mkln1 (99% identical), rabbit MKLN1 (96% identical), rat Mkln1 (96% identical), pig MKLN1 (96% identical), tropical clawed frog mkln1 (91% identical), zebrafish mkln1 (89% identical), Drosophila melanogaster muskelin (47% identical).
Diseases named in the same sentence as MKLN1 in open-access papers:
MKLN1 is named in the same sentence as 21 diseases in open-access papers, as found by Europe PMC text mining. Sharing a sentence is not in itself a finding about the gene and the disease. The quoted sentences say what the papers report.
acrodermatitis (3 papers, 2018 to 2021). An inflammatory skin condition affecting children. "Other known examples of functional variants at position +3 or +4 in 5′-splice sites include the MKLN1:c.400+3A>C variant in dogs with lethal acrodermatitis or the MBTPS2:c.1437+4C>T variant in horses with the brindle 1 phenotype." (PMID 34680893, 2021). "MKLN1 thus represents a novel candidate gene for human patients with unsolved acrodermatitis and/or immune deficiency phenotypes." (PMID 29565995, 2018). "Contrarily, a defect in the MKLN1 genes, that encodes muskelin 1, an intracellular protein not yet associated with zinc, was identified as a possible cause for lethal acrodermatitis." (PMID 33915721, 2021).
glioma (3 papers, 2014 to 2023). A benign or malignant brain and spinal cord tumor that arises from glial cells (astrocytes, oligodendrocytes, ependymal cells). "Cloning insertions from these SB-induced gliomas identified Sfi1, Csf1, Mkln1, Vps13a and Fli1 as common insertion sites (CISs) which are chromosomal regions that are insertionally mutated in more tumors than would be expected by random chance and represent candidate glioma genes." (PMID 25423036, 2014). "The MKLN1 expression level of the different glioma types in the Sun Brain dataset was consistent with previous studies." (PMID 36305248, 2023). "In other words, MET overexpression in this glioma with the G-CIMP-demethylated (C3) profile was possibly driven by the active MKLN1 promoter created by gene fusion, which led to activation of mitogen-activated protein kinase (MAPK) signaling." (PMID 30760837, 2019). "Compared with recurrent glioma tissues, we identified 774 differentially expressed (DE) mRNAs, 49 DE miRNAs, and 129 DE lncRNAs in primary LGGs and ultimately determined that the expression of MKLN1 was related to tumor recurrence in LGG." (PMID 36305248, 2023). "In addition, the MKLN1 locus is frequently hypomethylated and it is over-expressed at the mRNA level in GBMs compared to normal brain, therefore implicating MKLN1 as a glioma oncogene." (PMID 25423036, 2014). "Therefore, MKLN1 is a candidate driver of human glioma development." (PMID 25423036, 2014). "Moreover, MKLN1‐MET fusion was found in IDH‐mutant GBMs with G‐CIMP‐demethylated profile and can promote the proliferation and progression of glioma." (PMID 36305248, 2023).
bipolar disorder (2 papers, 2018 to 2022). A disorder of the brain that causes unusual shifts in mood, energy, activity levels and the ability to carry out day-to-day tasks. "A previous genome-wide association study (GWAS) showed that the human muskelin gene (MKLN1) variant (rs114034759-A) is significantly associated with increased risk of early-onset bipolar disorder and lower expression of MKLN1 protein levels in the hippocampal brain region." (PMID 35705737, 2022). "In humans, an intronic SNV in MKLN1 was associated with urinary potassium excretion in Korean adults and another intronic MKLN1 SNV with early bipolar disorder." (PMID 29565995, 2018).
acute myeloid leukemia (1 paper, 2024). Acute myeloid leukemia (AML) is a group of neoplasms arising from precursor cells committed to the myeloid cell-line differentiation. "Moreover, mutant alleles of MKLN1 may be associated with the genetic mechanism of primary chemoresistance in pediatric acute myeloid leukemia." (PMID 38460002, 2024).
Anxiety (1 paper, 2022). Intense feelings of nervousness, tension, or panic often arise in response to interpersonal stresses. "Further testing in the elevated plus maze and light–dark transition tests confirmed intact basal anxiety levels in Mkln1–/– mice." (PMID 35705737, 2022). "Given that little is known about the relevance of muskelin in vivo, we tested Mkln1-null mice and control littermates in a series of behavioral experiments designed to assess exploratory activity, anxiety-related behavior, and cognitive abilities." (PMID 35705737, 2022). "Here, it is unlikely that impaired habituation in Mkln1–/– mice stemmed from differences in anxiety-related behavior since the fraction of time spent in the open-field center was comparable between genotypes." (PMID 35705737, 2022).
asthma (1 paper, 2018). "A different SNV in the 5’-UTR of MKLN1 was associated with asthma in a population including patients with severe or difficult-to-treat asthma." (PMID 29565995, 2018). "A SNV in MKLN1 ranked among the top 100 SNVs associated with childhood asthma in a study sample of 429 affected-offspring trios from a European American population." (PMID 29565995, 2018). "Furthermore, MKLN1 has been associated with asthma in independent GWASs." (PMID 29565995, 2018).
breast carcinoma (1 paper, 2015). "MKLN1 has been previously associated with childhood asthma, SORBS1 with suicide risk and childhood obesity in Hispanics, SLC1A2 with fatty acid levels, essential tremor, and other traits, EPB41L4B with wound healing, PTPN3 with cancer, and FGF3 with breast cancer and deafness." (PMID 26569114, 2015).
cognitive deficit (1 paper, 2022). "Considering that diminished preference for social novelty may reflect a general cognitive deficit in Mkln1–/– mice, we extended our evaluation to address the contribution of muskelin to other forms of learning and memory." (PMID 35705737, 2022).
gastric carcinoma (1 paper, 2025). A carcinoma that arises from epithelial cells of the stomach. "We validated by immunoblot that MAEA depletion increased MKLN1 and ZMNYD19 abundances in both YCCEL1 and SNU-719 EBV+ gastric carcinoma cells." (PMID 41315365, 2025).
Hypertension (1 paper, 2017). The presence of chronic increased pressure in the systemic arterial system. "The group with heterozygotes of MKLN1 rs1643270 had the strongest risk effects on hypertension in the middle group for 24HUK obtained with the Kawasaki formula." (PMID 28273873, 2017). "MKLN1 rs1643270 and TENM4 rs10466739 were positively associated with hypertension." (PMID 28273873, 2017).
pulmonary fibrosis (1 paper, 2024). Chronic progressive interstitial lung disorder characterized by the replacement of the lung tissue by connective tissue, leading to progressive dyspnea, respiratory failure, or right heart failure. "In this study, we revealed that a novel circular RNA, MKLN1 (circMKLN1), was significantly elevated in two pulmonary fibrosis models (intraperitoneally with PQ, 50 mg/kg for 7 days, and intratracheally with BLM, 5 mg/kg for 28 days)." (PMID 38460002, 2024).
cancer (2 papers, 2015 to 2022). A tumor composed of atypical neoplastic, often pleomorphic cells that invade other tissues. "The role of TULP4, MKLN1, and ZNF532 in cancer is largely unknown." (PMID 35078526, 2022).
tumor (2 papers, 2016 to 2023). "In the present study, we used bioinformatics analysis to find that high MKLN1 expression in LGGs is associated with a poor prognosis and associated with tumor recurrence in LGGs, which has enriched the knowledge of MKLN1 dysfunction." (PMID 36305248, 2023). "We also checked whether the expression level of MKLN1, which holds the most optimal sensitivity and specificity in the AUC curve, may correlate with the tumor pathologic stage." (PMID 36305248, 2023).
MKLN1 also shares sentences with these, for which no sentence is quoted: attention deficit-hyperactivity disorder (1 paper); autism (1); childhood asthma (1); deafness (1); essential tremor (1); psychiatric disorder (1); schizophrenia (1); Silver Russel syndrome (1).